RPL22L1 (ribosomal protein L22 like 1)
Diseases named in the same sentence as RPL22L1 in open-access papers (continued):
Sharing a sentence is not in itself a finding about the gene and the disease.
cancer (14 papers, 2021 to 2025). A tumor composed of atypical neoplastic, often pleomorphic cells that invade other tissues. "Another RP, RPL22, is frequently mutated in cancers with microsatellite instability and its paralog RPL22L1 is often amplified." (PMID 40427096, 2025). "RPL22L1 is a ribosomal protein, and previous studies have confirmed that RPL22L1 expression is greater in cancer tissue and is linked to a worse prognosis." (PMID 35983409, 2022). "Numerous previous studies have demonstrated that the expression of RPL22L1 is aberrant in human cancer, and this feature is associated with a poor prognosis in malignant tumors." (PMID 33461173, 2021). "In addition, polyamines upregulated the expression of five ribosomal proteins, particularly RPS27A, RPL36A, and RPL22L1, which are associated with cancer malignancy." (PMID 40617352, 2025). "Interestingly, inactivation or loss of RPL22 in cancer is associated with increased expression of RPL22L1 and inclusion of exon 6 in MDM4, an event that promotes MDM4 expression by preventing formation of a ‘short’ MDM4 mRNA isoform (MDM4s) that is destroyed by nonsense-mediated decay." (PMID 38682900, 2024). "Experiments are in progress to clarify the polyamine-stimulatory mechanisms of eIF5A1, PKM, RPL36A, and RPL22L1 synthesis and functions of RPL36A and RPL22L1 during translation elongation in cancer cells." (PMID 40617352, 2025). "Our findings indicate that RPL22L1 exhibits abnormal expression patterns in various cancer types, including LUAD." (PMID 39207452, 2024). "In the present study, pan-cancer analysis demonstrated that RPL22L1 was significantly up-regulated in most tumors, including LUAD." (PMID 38577587, 2024). "Ribosomal protein RPL22L1 is a homologous analogue of RPL22 that plays pivotal roles in a variety of human cancers." (PMID 39509434, 2024). "Firstly, pan-cancer analysis showed that mRNA levels of RPL22L1 were up-regulated in most tumors, including LUAD." (PMID 38577587, 2024). "This study seeks to analyze the expression of RPL22L1 in pan-cancer and LUAD, utilizing data from the Cancer Genome Atlas (TCGA) database to evaluate its diagnostic relevance." (PMID 39207452, 2024). "LUAD tissue microarray was used for IHC to assess RPL22L1 protein levels (87 pairs of carcinomas/paracarcinomas were included in further analyses after exclusion of missing spots)." (PMID 38577587, 2024). "MLH1 and EPM2AIP1 were differentially expressed in all three cancers, RPL22L1 was included in the MAP signature of CRC and STAD, and H2AFJ was observed in both CRC and UCEC." (PMID 35428835, 2022). "In cancer tissues, RPL22L1 and INHBA were significantly upregulated in CRC with positive lymph nodes." (PMID 35909892, 2022). "Currently, there are limited studies on the function of RPL22L1 in cancer progression." (PMID 36625246, 2023). "Moreover, RPL22L1 is frequently amplified in certain cancer types." (PMID 40427096, 2025). "However, the role of RPL22L1 during mRNA decoding with eIF5A2 in cancer cells remains unclear." (PMID 40617352, 2025). "RPL22 and its paralog RPL22L1 (RPL22 Like-1) provide an interesting example of compensation, and in this case, it also extends beyond translation to influence cancer-related signaling pathways." (PMID 40427096, 2025). "WGCNA revealed dMMR/MSI-correlated gene modules, including INHBA and RPL22L1, which were upregulated; conversely, HMGCS2 was downregulated in MSI cancer." (PMID 35909892, 2022). "INHBA, RPL22L1, CAPZA1, and HMGCS2 showed significant differential levels in dMMR/MSI cancer tissues and were finally selected for further detection." (PMID 35909892, 2022).
cancer (continued). "As expected, the mRNA levels of RPL22L1, INHBA, and CAPZA1 were significantly higher in cancer than in normal tissues; conversely, HMGCS2 was significantly downregulated in cancer." (PMID 35909892, 2022). "Our GO enrichment revealed that RPL22L1, INHBA, and CAPZA1 had a significantly higher expression levels in MSI than in MSS, and these genes were also upregulated in CRC cancer tissues compared with their levels in matched normal tissues." (PMID 35909892, 2022). "The lncRNA GPRC5D-AS1 with CNVs driving the dysregulation of downstream cancer genes such as PRKCI, SEM1, TBL1XR1, IMPACT, and RPL22L1 further disturbed the activities of NOTCH signaling pathway that is usually inactivated in LUSC." (PMID 34925461, 2021). "Despite not being a direct WDR5 target gene, therefore, RPL22L1 expression is recurringly suppressed by WINi in responsive cancer cell lines." (PMID 38682900, 2024).
RPL22L1 also shares sentences with these, for which no sentence is quoted: adenocarcinoma (1 paper); breast carcinoma (1); colon sarcoma (1); gastric cancer (1); infectious disease (1); leukemia (1); lung carcinoma (1); mental retardation (1); metabolic disorder (1); neurological disorders (1); protein misfolding disorders (1); renal cell carcinoma (1).